RN7SKP66 (RN7SK pseudogene 66)
Gene: Miscellaneous RNA gene on chromosome 2 (43,772,120 to 43,772,350, reverse strand). Ensembl gene ENSG00000252490.
Homologues: Orthologues: chimpanzee 7SK (99% identical), mouse Gm54881 (45% identical), mouse Gm55389 (39% identical). Paralogues in human: RN7SKP131 (60% identical), RN7SKP63 (60% identical), RN7SKP216 (60% identical), RN7SKP221 (60% identical), RN7SKP62 (59% identical), RN7SKP189 (58% identical), 7SK (58% identical), RN7SKP124 (58% identical), RN7SKP294 (58% identical), RN7SKP297 (58% identical), RN7SKP75 (58% identical), RN7SKP79 (58% identical), and 282 more.